CXCR4 (C-X-C motif chemokine receptor 4)
Diseases named in the same sentence as CXCR4 in open-access papers (continued):
Sharing a sentence is not in itself a finding about the gene and the disease.
tumor (continued). "In the naive microenvironment, interactions involving Middle and Universal tumor cells were enriched in immune-related pathways such as MIF-CD74/CXCR4 and HLA-E-CD8A, suggesting a potentially immune-suppressive landscape." (PMID 39850495, 2024). "C-X-C motif chemokine receptor 4 (CXCR4) is necessary for tumor growth and metastasis, making it an attractive target in nuclear oncology." (PMID 39325320, 2024). "These recruited regulatory B cells also induce CXCR4 expression on tumor cell to promote cancer cell metastasis to the lymph node by increase the responsiveness to the pro-metastatic chemokine CXCL12." (PMID 38726320, 2024). "CXCR4, a representative G-protein-coupled receptor, plays an important role in mediating tumour-directed migration, invasion, and metastasis." (PMID 38706902, 2024). "The elevated levels of granzyme B+ B cells in tumor samples resulted from tumor cell chemotaxis through the MIF- (CD74 + CXCR4) signaling pathway." (PMID 38386050, 2024). "CXCR4 is a cell surface chemokine receptor that mediates cell dissemination, invasion, and proliferation present in tumor stem cells of a wide variety of tumors, such as glioma." (PMID 38607056, 2024). "The combination of cisplatin with a CXCR4 inhibitor offers potential benefits including tumor size reduction, minimizing resection-site impact, and enhancing patient quality of life." (PMID 39001388, 2024). "We discover CXCR4 antagonism via the ‘patching’ strategy has the ability to promote PDT in two ways: enhancing the repertoire of PDT and increasing tumor’s susceptibility to PDT." (PMID 38553476, 2024). "In tumor hypoxia, many chemokines can be released, including C-X-C motif chemokine 4 (CXCR4), which affects angiogenesis, immune surveillance, and the ability of tumor cells to metastasize." (PMID 38339244, 2024). "The MIF/CXCR4 axis was the most common ligand–receptor interaction between macrophages and tumor cells." (PMID 39464891, 2024). "In conclusion, our study adds to the evidence that CXCR4 expression in tumor tissue is a promising prognostic factor for STSs." (PMID 38893721, 2024). "Specifically, SOX12 transactivated CCL22, which resulted in the accumulation and enhanced activity of CCR4+Tregs within the tumor, whereas SOX18 up‐regulated CXCL12 expression, attracting CXCR4+TAMs and CXCR4+Tregs into the tumor." (PMID 39072947, 2024). "One study found that CXCL12 expression in the bone marrow in a lung cancer model provided a displacement signal for CXCR4 tumor cells, increasing their invasion of the environment." (PMID 38770000, 2024). "Administering AMD3100, a clinically approved CXCR4 inhibitor, has proved increased T cell accumulation within the tumor core." (PMID 39107856, 2024). "Hypoxia-inducible factor 1-alpha (HIF1-alpha), released from hypoxic tumor tissue, enhances the expression of VEGF, which subsequently upregulates CXCR4 on both tumor and endothelial cells, thereby promoting metastasis." (PMID 39723256, 2024). "We found that MIF/CXCR4 LR was the most common crosstalk between tumor cells and macrophages in G01 and G02." (PMID 39464891, 2024). "A higher concentration of CXCL12 in lymph nodes, lung, liver, and bone/bone marrow (BM) is thought to direct the metastasis of CXCR4-expressing tumor cells." (PMID 39001265, 2024). "The membrane receptor CXCR4 has been studied in several neoplasms and it is known to be overexpressed in aggressive tumors and associated with a worse prognosis." (PMID 38791878, 2024). "Inspired by developed CXCR4 antagonists, including plerixafor, ulocuplumab, and motixafortide, more small molecular antagonists or antibodies for pro-tumor chemokine ligands and their receptors can be developed and used in clinical practice." (PMID 38475811, 2024). "Taken together, these findings highlight the influence of tumor cells chemotaxis on GrB+ B cells through the MIF- (CD74 + CXCR4) signaling pathway." (PMID 38386050, 2024).
tumor (continued). "Strategies to modulate the tumor microenvironment, such as using CXCR4 inhibitors and antibody-drug conjugates (ADCs), are under clinical investigation and demonstrate potential therapeutic prospects." (PMID 39014460, 2024). "The modification of MSCs, such as overexpressing CXC chemokine receptor 4 (CXCR4) using a retroviral vector, is an improvement for homing to the tumor." (PMID 38399342, 2024). "Treating fresh human PDAC slices with a combination of PD-1 and CXCR4 blockade resulted in enhanced tumor cell death and lymphocyte expansion into the juxtatumoral compartment." (PMID 38835055, 2024). "These agents can disrupt the CXCL12/CXCR4 signaling pathway, thereby inhibiting tumor growth and metastasis." (PMID 39682247, 2024). "CXCR4 antagonists have demonstrated efficacy in restricting tumor growth in various experimental murine models." (PMID 38617537, 2024). "The current study demonstrated that the MIF - (CD74+CXCR4) ligand-receptor pair is significantly active in tumor cells with elevated IGF2BP1 expression." (PMID 39512352, 2024). "A recent study demonstrated that MSCs loaded with the chemotherapeutic agent paclitaxel had significantly improved tumor homing due to upregulation of CXCR4." (PMID 39576660, 2024). "We assessed the levels of CXCL12 and CXCR4 in the sera of 49 OC patients, considering the clinicopathological characteristics and comparing them with classical tumor markers (SCC-Ag and CEA) and markers of inflammation—CRP." (PMID 38673838, 2024). "Targeting CXCR-4 can dramatically lower overall tumor load and metastasis in multiple models of preclinical cancer, including ovarian, prostate, and breast cancers." (PMID 39065562, 2024). "Expression of CXCR4 and CCR5 on tumor was found to be associated with poor prognosis in this cohort with TNBC, and CXCR5 on tumor was associated with chemotherapy resistance." (PMID 39001456, 2024). "We have also recently shown that L3 can be successfully and stably radiolabelled with copper-64, resulting in high and specific CXCR4-mediated tumour uptake." (PMID 39204345, 2024). "Previous studies have reported that specific binding of the SDF-1/CXCR4 axis activates phosphorylation of multiple downstream signaling pathways to promote tumor cell survival." (PMID 39081954, 2024). "Immunotherapies are promising therapeutic approaches that can intervene in tumor growth using CXCR4 antibodies." (PMID 38791414, 2024). "In particular, the T1-weighted MR signal intensities in tumor site of anti-CXCR4-NaGdF4 NDs treated mice are stronger than those of Try-NaGdF4 NDs treated mice at all timed intervals within 12 h post-injection." (PMID 38982161, 2024). "In vitro, cultures have identified CXCR4 and miR‐200 as potential targets in modulating tumor cell plasticity." (PMID 38193115, 2024). "A study showed that inhibition of the CXCL12/CXCR4 axis suppressed the accumulation of TAMs and sepsis-induced tumor progression in mice." (PMID 39403370, 2024). "Tumor-associated lymphatic endothelial cells upregulate CXCL12 expression, which then interacts with CXCR4 in T cells." (PMID 39107856, 2024). "CXCR4 expression as membranous staining of tumor cells was correlated positively with histopathological grade (p = 0.036) and negatively with lymph node metastasis (p = 0.036)." (PMID 39001456, 2024). "Correlation analysis revealed that CXCR4 showed significant differences in clinical features of age, neoplasm histologic grade, OS, pathologic T, and tumor stage." (PMID 38221932, 2024). "It is a type 1 HSV that expresses the cytokines IL-12 and IL-15 and the alpha subunit of the IL-15 receptor under the control of the tumor-specific C-X-C chemokine receptor type 4 (CxCR4) promoter." (PMID 39204331, 2024). "Tumor’s progression is marked by an increase in the IFF that plays a critical role in GBM cells migration through increasing their expression of CXCR4 and secretion of CXCL12 along white matter tracts, blood vessels, and subpial regions." (PMID 39715221, 2024).
tumor (continued). "Monocytes are recruited to tumor sites via CCR2 signaling, where tumor cell-secreted TGF-β induces CXCR4, stimulating them to migrate toward CXCL12-expressing perivascular cancer-associated fibroblasts (CAFs)." (PMID 39516356, 2024). "Blocking CXCR4 signaling prevents the accumulation of perivascular macrophages and delays tumor regrowth." (PMID 39555068, 2024). "A study by L. Gorchs and colleagues showed that CAFs down-regulate the expression of CXCR3 and CCR5 while upregulating CXCR4 expression in both 2D and 3D pancreatic tumor cultures, thereby inhibiting T cell tumor infiltration towards CXCL10." (PMID 39596815, 2024). "In BC, EPCs that express VEGFR1, VEGFR2, and CXCR4 are attracted to the tumor site due to estrogen-mediated HIF-α upregulation." (PMID 39609700, 2024). "Inhibition of CXCR4 by Plerixafor or selective Ly6C targeted genetic ablation in monocytes rescues mice from anti-VEGFR2 induced tumor progression." (PMID 39100682, 2024). "CXCR4 overexpression has also been combined with CARs targeting either CD19 or epidermal growth factor (EGFR)vIII in NK cells to enhance migration toward tumor cells and the retention of endogenous and CAR-mediated cytotoxic activities." (PMID 38443448, 2024). "Inhibition of CXCR4-CXCL12 mobilizes CD8+ T cells in the tumor and synergizes with anti-PD-L1 immunotherapy; CXCR4 antagonist AMD3100 is used to improve efficacy of bortezomib treatment and anti-PD-1 and anti-CTLA-4 therapy in breast cancer mouse models." (PMID 39596815, 2024). "The BALB/c nude mouse bearing MDA-MB-231 tumor was used for evaluating the tumor-targeting capacity of anti-CXCR4-NaGdF4 NDs through intravenous injection of anti-CXCR4-NaGdF4 NDs and Try-NaGdF4 NDs via tail vein, respectively." (PMID 38982161, 2024). "In 4 patients including 1 relapsed DLBCL, immuno-PET using 68Ga-labeled, CXCR4-targeting peptide (pentixafor) resulted in excellent tumor uptake and contrast." (PMID 38464386, 2024). "C-X-C motif chemokine receptor 4 (CXCR4) is overexpressed in a multitude of cancers, including neoplasms of hematopoietic origin." (PMID 38190998, 2024). "Pretreatment with the unlabeled precursor significantly decreased the uptake in A549/CXCR4 tumor (2.08 ± 0.36 vs. 1.11 ± 0.19%ID/mL, P < 0.01)." (PMID 39431004, 2024). "This pattern underscores the crucial role of CXCR4 in not only facilitating cellular communication and migration but also enhancing the metastatic capabilities of tumor cells across diverse cancer types." (PMID 39195225, 2024). "Considering the role CXCR4 plays in tumor progression and metastasis, its inhibition offers significant potential for cancer treatment." (PMID 39070795, 2024). "Highly selective small molecule CXCR4 antagonist suppresses tumor growth and prevents distant metastasis and TAMs infiltration in HCC, while the canonical CXCR4 inhibitor, AMD3100, reduces MDSCs-mediated murine HCC cell migration to the spleen and liver." (PMID 37142825, 2024). "PET/CT image of CXCR4 expressing melanoma tumor bearing mice clearly delineated the tumor, with high contrast, at 1 h post-injection." (PMID 39050235, 2024). "In contrast, a correlation of Ki67 with CXCR4 expression within the same tumor tissue was found in immunohistochemical analyses." (PMID 38896128, 2024). "CXCL12 plays a crucial role in tumour growth and metastasis by binding to its receptor, CXCR4, in the tumour cell membrane." (PMID 38766687, 2024). "Since CXCR4 levels were elevated in tumor and vascular cells of GBM, it was suggested that pseudopalisade cells around hypoxic areas of necrosis overexpress CXCR4 under the control of HIF-1α." (PMID 39055895, 2024). "C-X-C motif chemokine receptor 4 (CXCR4) is a transmembrane G-protein-coupled receptor crucially involved in tumor dissemination of varying malignancies." (PMID 38082196, 2024).
tumor (continued). "CXCR4 plays a critical role in the metastatic spread of different types of tumor cells mediating their homing to organs which express the specific ligand, C-X-C motif chemokine ligand 12 (CXCL12)." (PMID 39465008, 2024). "Spatial analysis of KS/PDX biopsies confirmed that CXCL12 was higher in tumor regions with fibroblast-clusters, while expression of CXCR4, the receptor of CXCL12 was higher in regions with KS signature clusters." (PMID 39386738, 2024). "After intravenous injection, P-BS-CM1-Cy5 with the CXCR4-specific BS exhibited substantially higher tumor accumulation than P-CM1-Cy5 that passively reached the tumor." (PMID 38553476, 2024). "With its conventional receptor, CXCR4, CXCL12 modifies immunity by immune cell recruitment and polarization, such as altering tumor-associated macrophages and T cells, eventually promoting malignancies." (PMID 38898023, 2024). "CXCL12 and CXCR4 are involved in developing tumor progression and distant metastases and can lead to resistance to chemotherapy in solid tumors." (PMID 38770000, 2024). "Some studies have shown that CXCR4 is upregulated in human HCC cells, and the CXCL12–CXCR4 axis promotes tumor migration and angiogenesis in HCC." (PMID 38767772, 2024). "It has been reported that, via integrating scRNA-seq with bulk data, CXCR4 expressed by tumor-infiltrating B cells has a poor prognosis, suggesting that CXCR4 can be an attractive therapeutic target for GC." (PMID 39519285, 2024). "Next, we assessed the functional characteristics of aged CXCR4+ neutrophils to investigate their role in supporting tumor progression." (PMID 39447112, 2024). "Multicolor immunofluorescence staining indicated the high tracer uptake in certain patients was mainly due to the high expression of CXCR4 in tumor cells, followed by macrophages." (PMID 39431004, 2024). "The SDF-1α/CXCR4 signaling pathway plays an essential role in various physiological processes, including cell transport, angiogenesis, embryogenesis, tumor invasion, and metastasis." (PMID 38571956, 2024). "They show that T22-GFP accumulates in CXCR4 overexpressing tumor tissues, with minimal accumulation in other organs." (PMID 39559553, 2024). "Another approach to recruiting T cells into tumor is to use constructs expressing a chemokine receptor, such as CCR2, CCR2b, CXCR3, CCR4, CCR7, CXCR2, or CXCR4, which can interact with the relevant tumor-derived chemokine." (PMID 38927974, 2024). "CXCR4 not only enhances tumor cell adhesion to extracellular matrix components and endothelial cells but also promotes their chemotactic movement through tissues, facilitating invasion into blood vessels and distant organs." (PMID 39001498, 2024). "These tumor‐bearing mice were adoptively transferred with control or CXCR4+ B cells and saline or CXCL12." (PMID 39422063, 2024). "Taken together, these findings suggest that delayed neutrophil apoptosis induced by tumor‐derived G‐CSF/GM‐CSF significantly contributes to the accumulation of aged CXCR4+ neutrophils in vivo." (PMID 39447112, 2024). "Such insights highlight the potential of targeting the SDF-1/CXCR4 axis as a therapeutic strategy for disrupting the CSC niche within the CRC tumor microenvironment." (PMID 39195225, 2024). "In the context of VM, our findings reveal a propensity for increased communication involving IIF and CD74+CXCR4 within each signaling pathway in the tumor group." (PMID 39165361, 2024). "Accordingly, recruiting CXCR4+ MDSCs, M2 macrophages, and Tregs can suppress anti-tumor immune responses, inducing tumor growth and progression." (PMID 39070795, 2024). "Research has shown that CXCL12 and CXCR4 impact angiogenesis and tumor growth, as well as invasion and metastasis." (PMID 38791414, 2024). "The findings reported herein demonstrate that engineered overexpression of CXCR4 bestows BCMA CAR-NK-92 cells with an increased ability to eliminate BCMA-expressing tumor cells in vitro." (PMID 38979422, 2024).
tumor (continued). "This study systematically analyzed the clinicopathological features and prognosis and investigated the expression of CXCR4 in tumor and adjacent tissues of patients with GEP-NENs G3 who underwent surgical treatment in Qilu Hospital of Shandong University." (PMID 38524630, 2024). "We have demonstrated that the expression of SDF-1 by CAFs directly influences tumor behavior, enhancing aggressiveness through CXCR4 targeting." (PMID 39195225, 2024). "This suggests that VEGF inhibition does not directly attack tumors, but indirectly exerts an antitumor effect by approaching tumor blood vessels, which is similar to the results of the current study using CXCR4 inhibitors." (PMID 39001388, 2024). "In the UMAP and heatmap of the scRNA-seq dataset, CXCR7 was predominantly expressed in tumor-cell clusters, particularly in Tumors 2, 3, and 6, whereas CXCR4 was predominantly expressed in both myeloid-cell and T-cell clusters." (PMID 38898023, 2024). "It is a very potent and selective antagonist of chemokine receptor C-X-C chemokine receptor type 4 (CXCR4), inhibiting tumor growth and metastasis, as well as activating the immune response in the tumor microenvironment." (PMID 37513908, 2023). "For example, disrupting CXCL12-CXCR4 signaling by AMD3100, a small molecule inhibitor of CXCR4, demonstrated a synergistic anti-tumor activity in combination with anti-PD-1/PD-L1 therapy in mouse models of PDAC." (PMID 37771596, 2023). "As a whole, avidin-PLGA nanoparticle surface tagged with biotinylated DV1 peptide ligand is a strategy for preventing tumor progression in CXCR4-expressing cancer cells." (PMID 38004925, 2023). "Research has shown that CXCR4 was overexpressed in various tumor cells, such as breast and prostate cancers." (PMID 38129870, 2023). "Patients harboring low/medium expression of CXCR4 in tumor samples showed a worse overall survival (OS) (p-value = 0.0055)." (PMID 38096163, 2023). "In various tumor entities, however, an intracellular protein localization of CXCR4 has been described." (PMID 36982302, 2023). "Radiopharmaceutical accumulation takes place in CXCR4-expressing malignant and metastatic lesions (with high tumour retention) as well as in the liver, kidneys, and bone marrow." (PMID 39355052, 2023). "By keeping CXCR4-expressing T cells away from the juxtatumoral compartment, the tumor escapes recognition and destruction by tumor-specific lymphocytes." (PMID 37966614, 2023). "Comparison of CXCR4 expression in metastatic tissue with primary tumor expression revealed a significantly higher IR score for cytoplasmic expression in metastatic tissue, whereas nuclear expression was significantly stronger in primary tumor tissue." (PMID 36982302, 2023). "The simultaneous systemic administration of the bioorthogonal SPIONs in tumor-bearing mice demonstrated the signal-enhancing ability of these ‘smart’ self-assembling nanomaterials for preventing tumor growth (positive for CXCR4 and MMP2/9 metalloproteases." (PMID 38004925, 2023). "CXCR4 is overexpressed in GBM and GSCs, and correlates with tumor size, progression, and recurrence, while the CXCL12/CXCR4 pathway is associated with GBM cell migration." (PMID 37325516, 2023). "CXCR4 activation induced tumor cell chemotaxis and increased the production of vascular endothelial growth factor." (PMID 39355049, 2023). "Compared with the primary tumor tissues, the residual disease samples exhibited higher CXCR4 protein after treatment with trastuzumab and chemotherapy (P < 0.05)." (PMID 37280713, 2023). "Interactions of tumor cells with the BM microenvironment involve preferred communication with myeloid cells through the MIF/CD44/CD74/CXCR4 and MK/LRP1/NCL axes." (PMID 37365178, 2023). "For example, a phase II trial has shown the beneficial effects of combining an anti-PD-1 therapy with CXCR4 blockade to promote T cell tumor infiltration in PDAC57." (PMID 37669956, 2023).